FASN (fatty acid synthase)
Diseases named in the same sentence as FASN in open-access papers (continued):
Sharing a sentence is not in itself a finding about the gene and the disease.
cancer (continued). "Mounting evidence indicates that, besides de novo lipogenesis, the mechanisms whereby FASN fuels cancer proliferation and survival could be multiple." (PMID 39064589, 2024). "Additionally, TAMs are activated by FASN and peroxisome proliferator-activated receptor β/δ (PPARβ/δ), induced by macrophage colony-stimulating factor (M-CSF) secreted from cancer cells, which further promotes tumor progression." (PMID 38765144, 2024). "Cancer cells also increase fatty acid synthesis and lipogenesis to meet the demand for new membrane formation, with enzymes like acetyl-CoA carboxylase, stearoyl-CoA desaturase 1, ATP-citrate lyase, and fatty acid synthase frequently upregulated." (PMID 39795950, 2024). "There are differences in the results of lipid synthesis by FASN between normal and cancer tissues." (PMID 38819674, 2024). "FASN is upregulated in several types of cancers and it is critical for boosting FA production." (PMID 39337514, 2024). "In this context, mathematical modeling confirmed that targeted FASN gene elimination in cancer cells leads to an accelerated extinction kinetics upon interaction with T cells, as shown by the increased cytolytic rates associated with the interaction between FASNKO cells and T cells." (PMID 39349429, 2024). "Specifically, we examined how FASN-regulated mitochondrial OXPHOS function and priming status might affect the susceptibility of cancer cells to T cell-mediated killing." (PMID 39349429, 2024). "Now, we demonstrated that treatment of PCC-cancer-derived cell lines with a polyamine analogue inhibitor DENSPM results in a broad downregulation of gene expression associated with fatty acid synthesis and processing, including FASN, SCD1, FADS2, and SREBPs." (PMID 39337514, 2024). "This suggests that cancer cells potentially upregulate multiple other metabolic pathways to compensate for FASN inhibition and this may be conserved among multiple cancer types." (PMID 39149696, 2024). "It has been proposed that FASN can be degraded via macroautophagy in human cancer cell lines." (PMID 38539242, 2024). "FASN is overexpressed in various cancers and is vital for the enhanced production of FAs." (PMID 39551780, 2024). "However, FASN is significantly upregulated in many forms of human cancer as the increased lipid synthesis from FASN activity is essential for the membrane production required for highly proliferating tumor cells." (PMID 38467328, 2024). "The expression level of FASN in cancer cells can be regulated at various biological levels." (PMID 38195819, 2024). "In addition, various post-translational modifications, including ubiquitination, acetylation and sumoylation, have emerged as important contributors to FASN upregulation in multiple cancers." (PMID 38195819, 2024). "Targeting the lipid and cholesterol dependence of cancer cell inhibitor agents directed against lipogenic enzymes (FASN, ACLY and ACC) has been the subject of numerous studies; and their efficacy as anticancer therapies has been proven in various preclinical models of carcinogenesis." (PMID 38263248, 2024). "In many cancers, FASN is overexpressed, driving tumour growth and survival." (PMID 39796683, 2024). "Additionally, increased lipids in cancer cells are a marker of aggressive tumors, and increases in lipogenic enzymes, such as acetyl-CoA carboxylase, fatty acid synthase (FASN), and ATP citrate lyase, are found in almost all advanced tumors." (PMID 39007351, 2024). "Additionally, it suppresses the fatty acid synthase gene and other important genes related to fat metabolism, impairing mitochondrial activity and making cancer cells deprived of energy." (PMID 39323697, 2024). "Fatty acid synthase expression occurs predominantly in proliferating fetal cells, implying that reactivation of FA synthesis in cancer cells may be a signal to return a stemness maintenance status." (PMID 38584256, 2024). "FASN is tightly regulated by PTMs, making it as an appealing target for cancer therapy." (PMID 39551780, 2024).
cancer (continued). "Consistently, FASN inhibition increased the chemosensitivity of cancer cells to cisplatin." (PMID 39624081, 2024). "Moreover, many active components derived from Chinese herbs displayed FASN inhibitory activity in various types of cancers, such as quercetin, osthole, and oridonin." (PMID 38765144, 2024). "RV dramatically decreased lipid production in many cancer cell lines by downregulating FASN." (PMID 39273552, 2024). "Furthermore, several cancers require fatty acid synthase (FASN) activity to survive, suggesting that the response to low lipid synthesis is cell death rather than lipid checkpoint regulation." (PMID 38499565, 2024). "Rethinking the role of FASN as a signal transducer in cancer pathogenesis may provide molecularly driven strategies to optimize FASN as a long-awaited target for cancer therapeutics." (PMID 38158755, 2024). "We previously demonstrated that genetic or chemical ablation of FASN-driven lipogenesis elevates the primed state of cancer cells by upregulating pro-death BH3-only proteins such as BIM, PUMA, and NOXA, heightening mitochondrial priming and shifting cells toward a primed-for-death state." (PMID 39349429, 2024). "PGG inhibits glioma cancer cells by suppressing fatty acid synthase and activating caspase-3." (PMID 37375411, 2023). "Finally, to investigate the impact of FASN inhibition on mitochondrial respiration in the two cancer systems, we performed a Mito Stress Test." (PMID 36650542, 2023). "Further, EGFR and FASN form a positive feedback loop in cancer cells, which needs to be investigated in Cr(VI)-transformed lung cells as it may provide more mechanistic evidence of the role of FASN in Cr(VI)-transformed cell growth." (PMID 38069382, 2023). "Indeed, using RNAseq analysis, we were able to see higher expression of FASN in cancer cells cultured in conditioned medium containing exogenous periostin." (PMID 38049490, 2023). "Additionally, FASN induced in cancer cells by elevated exogenous periostin plays important roles in lipid metabolism to generate excessive amounts of free fatty acids, which are then broken down into acetyl-CoA52." (PMID 38049490, 2023). "Furthermore, we demonstrated the regulatory circuit among EGF signaling, CSN6 signaling, FASN expression level, and accumulation of fatty acids during cancer formation." (PMID 37202390, 2023). "FASN is being explored as a drug target because it enables cancer cells to survive in tumors." (PMID 36996232, 2023). "Moreover, FASN is significantly upregulated in cancers of the breast, ovary, and pancreas, especially when accompanied by treatment-resistant features." (PMID 36604718, 2023). "As mTOR activity is commonly dysregulated in the majority of human cancers, our work raises the plausible hypothesis that part of the beneficial effect of FASN inhibition in cancer treatment may be due to the concomitant drop in mTORC1 signalling." (PMID 37563253, 2023). "Due to the insufficiency of carbohydrates during the early stage of tumor tissue, cancer cells may activate FASN to produce long-chain fatty acids as an energy alternate for survival." (PMID 37124526, 2023). "However, cancer cells tend to exhibit increased fatty acid synthase activity to endogenously supply fatty acids to cancer cells in order to meet the high demand." (PMID 36652113, 2023). "Moreover, fatty acid oxidase and fatty acid synthase (FASN) have been shown to sustain survival of cancer cells in TME and increase resistance to anoikis and chemotherapy and spheroid formation in HGSOC lines." (PMID 37448521, 2023). "Therefore, to accurately predict the sensitivity of cancer cells to FASN inhibitors, we first need to understand the interactions between the different metabolic networks of cancer cells." (PMID 37056351, 2023). "Increased FASN levels and fatty acid de novo synthesis have been observed in various fatty tissue-rich tumors, including breast, gastric, prostate, and ovarian cancers." (PMID 37064140, 2023).
cancer (continued). "FASN inhibition leads to a decrease in tumor progression through several mechanisms, such as alteration of plasma membrane structure, an increase in cancer cell apoptosis, decrease in palmitate synthesis, and inhibition of Wnt, Akt, and β-catenin oncogenic signaling pathways." (PMID 37760840, 2023). "Consequently, FASN promotes metastasis, making the enzyme a prime target for preventing cancer progression and cancer cells spreading." (PMID 36934087, 2023). "Many cancers, including breast, are dependent on de novo fatty acid synthesis and as a result there has been a concerted effort to capitalize on this dependence by developing inhibitors of fatty acid synthetase (FASN)." (PMID 37306503, 2023). "Importantly, dual inhibition of OGT and FASN synergized to induce the death of cancer cells in vitro." (PMID 37838167, 2023). "Our data are in line with a recent study that showed that inhibition of FASN could trigger cancer cell death via interactions with the BCL-2 family and that upregulation of pro-death BH3 only proteins increase mitochondrial apoptosis priming." (PMID 37270622, 2023). "Moreover, the up-regulation of FASN expression can further stimulate the processes of endothelial cell recruitment and induction of the vasculature of cancer cells, which promotes cell growth and correlates with poor prognosis." (PMID 38003694, 2023). "Due to the role of FASN in de novo fatty acid synthesis, our data suggest that lipid metabolism in cancer cells could be altered through increased FASN expression in response to an environment with higher periostin levels." (PMID 38049490, 2023). "The role of the fatty acid synthase (FASN), a known factor in developing cancer, in the development of SACC was investigated in an in vitro study, which confirmed that FASN promotes the epithelial-mesenchymal transition (EMT), invasion, and metastasis of SACC cells." (PMID 37159817, 2023). "Hence, while we show that mutant GNAQ regulates FASN expression in UM, there are other factors that can also regulate FASN in UM and other cancer types." (PMID 37444561, 2023). "FASN also plays a critical role in overall metabolic remodeling of cancer cells." (PMID 37444561, 2023). "In addition, targeting lipid metabolism enzymes such as acetyl-CoA carboxylase (ACC) and fatty acid synthase (FASN) has also shown promise in reducing cancer growth." (PMID 37233659, 2023). "Lipid rafts also contribute to the activity of FASN in cancer cells." (PMID 37256177, 2023). "Notably, aberrant upregulation of FASN in cancer cells reduced the expression of E-cadherin, which is a vital epithelial adherens junction protein." (PMID 36922854, 2023). "However, little is known about cancer cell sensitivity to FASN inhibitors, thus creating a bottleneck for their therapeutic application." (PMID 36650542, 2023). "Orlistat, a FASN inhibitor, exerted anti-cancer effects both in vivo and in vitro." (PMID 37416772, 2023). "Studies report upregulated fatty acid synthase (FASN) expression in cancer and pre-cancer cells." (PMID 37173619, 2023). "Finally, metformin has also been found to reduce the production of fatty acid synthase, which is known to be oncogenic and significantly upregulated in cancer cells." (PMID 37760509, 2023). "Because FASN and SCDs that produce these saturated and unsaturated FAs are suggested to play essential roles in cancer progression, our findings that higher PC species, including FA (16:0) and FA (16:1), reflected shorter RFP and disease progression are compatible with these previous reports." (PMID 36707819, 2023). "In PDAC, FASN inhibition led to decreased cancer cell proliferation and increased apoptosis." (PMID 36675307, 2023). "FASN is the most investigated fatty acid metabolism enzyme in cancer at present." (PMID 36994237, 2023). "Moreover, FASN inhibitors can enhance the effects of chemotherapy drugs, restore tumor sensitivity to treatment, and inhibit tumor growth in resistant cancer cells." (PMID 38189049, 2023).
cancer (continued). "Although upregulation of FASN, GLUD1, and G6PD in the high-risk group barely missed statistical significance, these enzymes deserve attention given their biological significance in cancer and metabolism." (PMID 37760474, 2023). "The methylation of the FASN promoter in DNA can be used to serve as a new biomarker for cancer." (PMID 37920207, 2023). "Positive FASN protein expression was associated with increased tumor aggressiveness and was an independent predictor of shortened cancer-specific survival, suggesting that FASN could be a predictive indicator of disease prognosis." (PMID 36834678, 2023). "FASN regulation will affect its upstream metabolites and downstream metabolites, which in turn impacts on several important biological functions involved in cancer or disease." (PMID 37202390, 2023). "Therefore, in cancer cells, abrogation of lipid synthesis through inhibition of lipogenic enzymes, such as the FASN, has a strong impact on general metabolism, resulting in decreased cell growth/proliferation and increased apoptosis of cancer cells." (PMID 36677614, 2023). "Similarly, various aspects of fatty acid metabolism and lipogenesis upregulated in cancer cells are targeted by inhibiting the regulatory enzymes such as FASN." (PMID 36618350, 2022). "Additionally, mir-497-5p was significantly downregulated in multiple cancers and was significantly negatively correlated with FASN in twelve cancer types." (PMID 36555243, 2022). "Several key enzymes involved in the de novo synthesis pathway, such as ACLY, ACC, and FASN, are significantly up-regulated, suggesting that these enzymes may be potential drug targets for inhibiting cancer progression." (PMID 36588702, 2022). "Fatty acid synthase (FASN) which catalyzes the condensation of acetyl coenzyme A produces excess fatty acids to meet the demand for enough plasma membrane lipids in cell proliferation of cancer." (PMID 35957912, 2022). "TVB-3166, TVB-2640, and omeprazole inhibit the FASN to inhibit cancer proliferation." (PMID 36618350, 2022). "However, the majority of cancer cells overexpress lipogenic enzymes, including fatty acid synthase (E.C. 2.3.1.85; FASN) and exhibit a dependency on de novo fatty acid synthesis." (PMID 35268652, 2022). "Importantly, high levels of FASN were significantly negatively correlated with tumor immune infiltration in 35 different cancers." (PMID 36555243, 2022). "FASN may serve as an oncogenic factor due to its role in regulating cancer cell fatty acid synthesis or driving aberrant lipogenesis in cancer cells." (PMID 35597782, 2022). "A recently published study suggests that FASN activity could be essential during the initial steps of the transformation process and, thus, can be a target for cancer prevention." (PMID 35742953, 2022). "In ovarian clear cell carcinoma, cancer grade was significantly correlated with FASN expression." (PMID 35216285, 2022). "Since EMT is critical to cancer metastasis, the decrease of FASN indicated the hypothesis that DS−1 could inhibit the EMT pathway." (PMID 35744840, 2022). "We examined the relationships between FASN expression and the pathological grades and stages of many tumor types, given FASN expression is altered following the initiation of numerous highly lethal cancer types." (PMID 36555243, 2022). "In contrast, miR-21 increased intracellular phospholipids and TG, and enhanced gene expression of key enzymes in lipogenesis, such as fatty acid synthase (Fasn), acetyl-CoA carboxylase (Acaca), and fatty-acid binding protein 5 (Fabp5) in A549 cells or H1703 cancer cells." (PMID 36360201, 2022). "Moreover, much clinical advancement has been made in targeting FASN and the de novo lipid synthesis pathway in numerous cancers including breast." (PMID 36096767, 2022). "Inhibition of FASN activity can decrease cell proliferation and induce apoptosis in cancer cells." (PMID 35566090, 2022).
cancer (continued). "As overexpression of FA synthase (FASN) in BC conferred chemoresistance in vitro, pharmacological targeting of FASN could make a range of cancer cell types sensitive to chemotherapy." (PMID 35432381, 2022). "Since FASN is elevated in both cancer cells and CAFs, FASN could be a potential epithelial–stromal common target proposed in our previous study." (PMID 36115986, 2022). "FASN is overexpressed in most cancer types to promote lipogenesis." (PMID 36618350, 2022). "FASN can also have an immunoregulatory role to support the immune avoidance in these cancer types." (PMID 35448537, 2022). "Surprisingly, almost all major histocompatibility complex molecules (MHCs), except TAP2, were negatively correlated with FASN expression in a variety of malignancies, especially in LGG, when we examined the correlation between FASN expression and MHCs in pan-cancer." (PMID 36555243, 2022). "Moreover, research articles provided the evidence that a decrease of FASN-mediated or HMGCR-regulated biosynthesis caused the suppression of cell growth, migration, and the survival pathways in cancer cells." (PMID 36362924, 2022). "Importantly, the effects of USP13 on SCLC cancer stemness maintenance and lipogenesis were abrogated by FASN depletion." (PMID 35898882, 2022). "Therefore, to identify FASN-mediated vulnerabilities which can be efficiently targeted in cancer, it is very important to understand the contribution of FASN to CRC initiation in the context of the in vivo in a mouse model with ad libitum feeding." (PMID 35742953, 2022). "FASN was found to be associated with poor prognosis in RCC and other cancers." (PMID 35328822, 2022). "Targeting FASN by FASN inhibitors is useful to sensitize cancer cells to chemotherapies." (PMID 35646898, 2022). "Moreover, higher FASN expression was correlated with the presence of more aggressive disease and poor prognosis in several cancer types, including RCC." (PMID 35328822, 2022). "Fatty acid synthase plays an important role in cancer pathogenesis." (PMID 36232754, 2022). "However, upregulation of FASN represents a common phenotypic alteration in many cancers, which indicates that lipogenic oncogenes have indispensable roles in tumor growth and tumor survival." (PMID 35216362, 2022). "FASN is highly expressed in most cancers, and its high expression indicated poor prognosis." (PMID 36555243, 2022). "Even though numerous studies show the benefit of targeting FASN in cancer including CRC, knowledge about the contribution of lipid synthesis to CRC initiation is very limited, and the utility of this pathway as a therapeutic target for the early stages of this disease is unclear." (PMID 35742953, 2022). "Research shows that FASN is frequently expressed in different types of cancers, including BC." (PMID 36230935, 2022). "Therefore, FASN was considered one of the more than 600 most promising therapeutic drug targets in human cancers." (PMID 35401213, 2022). "Increased FASN fulfils the phospholipids requirement for dividing cancer cells and plays a crucial role in cancer cell development and proliferation, hence it may be an appealing target for cancer therapy." (PMID 35879772, 2022). "Thus, pharmacologically targeting fatty acid synthase can sensitize multiple types of cancer cells to chemotherapy in vitro and in vivo." (PMID 35785165, 2022). "Therefore, FASN is regarded as an antitumor target, which is related to the survival of cancer cells." (PMID 35566090, 2022). "FASN not only integrate several signaling pathways that regulate the metabolism, proliferation and survival in tumor cells, but also play an active part in the development, maintenance and metastatic progression of human cancers." (PMID 35791446, 2022). "Overexpression of FASN was suggested to decrease cancer-specific survival." (PMID 35328822, 2022). "Since FASN is a key enzyme involved in USP13-promoted cancer stemness, we further examined whether FASN inhibitor could be a favorable treatment strategy." (PMID 35898882, 2022).